CHAF1B (chromatin assembly factor 1 subunit B)
Diseases named in the same sentence as CHAF1B in open-access papers (continued):
Sharing a sentence is not in itself a finding about the gene and the disease.
retinoblastoma (1 paper, 2025). A malignant tumor that originates in the nuclear layer of the retina. "The highest agreement between RNA and protein level was observed for DDB2, CHAF1B, and POLD1, which were upregulated in retinoblastoma, and RHO, PDE6A, and CRABP1, which were downregulated." (PMID 40395327, 2025).
cancer (18 papers, 2014 to 2025). A tumor composed of atypical neoplastic, often pleomorphic cells that invade other tissues. "Higher expression of CHAF1B is associated with increased Κi-67 staining of cancer cells, and with aggressive clinical behaviour." (PMID 34073937, 2021). "The overexpression of CHAF1B is associated with histological grading and may serve as an indicator of poor prognosis in cancer patients." (PMID 41049428, 2025). "CHAF1B has emerged as a promising predictive biomarker for therapeutic response monitoring in cancer." (PMID 41049428, 2025). "For example, MAPK8IP2, ADAMTS12, and CHAF1B were upregulated in over five cancer types, while HHIP, PROX1, and PLCG2 were downregulated in over five cancer types." (PMID 35654793, 2022). "Experiments in human ovarian cancer cell lines suggest that CHAF1B enhances the proliferation of cancer cells and inhibits apoptosis, thus mediating tumour growth." (PMID 34073937, 2021). "Researches have shown that up-regulated CHAF1B is significantly correlated with poor outcomes and that CHAF1B has potential in predicting the prognosis in several cancers, including CC." (PMID 33616161, 2021). "Cellular experiments confirmed that knockdown of CHAF1B inhibits the proliferation and invasion of cancer cells and inhibits the growth of xenografts in vitro." (PMID 32508530, 2020). "Combined with public database, PCR, WB and protein chip results, we know that CHAF1B is higher in cancer tissues than in adjacent tissues, and CAHF1B is the highest in resistant strains." (PMID 32508530, 2020). "In the pan-cancer cohort of the WG-505 dataset, OncodriveFML identified BORA and CHAF1B as putative driver genes from the mutations in their 3′ UTR regions." (PMID 27311963, 2016). "Therefore, it is speculated that CHAF1B plays an important role in the pathogenesis of malignant tumors." (PMID 33616161, 2021). "Previous studies have demonstrated roles for the histone chaperones such as HIRA, CHAF1B and the molecular co-chaperone DNAJC9 in preventing CENP-A mislocalization in human cancer cells lines." (PMID 39135477, 2024). "The prognostic genes for ACC and LIHC had a shared enrichment for SWI/SNF chromatin remodeler genes with SMARCD1 in ACC, and ARID1A and CHAF1B in LIHC, being the most significantly prognostic SWI/SNF genes (P < 0.0001) in these two cancer types." (PMID 37973839, 2023). "Moreover, previous studies have implicated ACKR3, CHAF1B, CHEK1, and COL11A1 as being involved in cancer cell proliferation, while CA9, CHAF1B, and COL11A1 play roles in cancer invasion and migration." (PMID 38652547, 2024). "In summary, our studies show that proper deposition of canonical histones by histone chaperones such as CHAF1B prevents CIN and that defects in these pathways might contribute to aneuploidy in CENP-A-overexpressing cancers." (PMID 37129573, 2023). "Additionally, UBASH3B, CASP1, CARM1, CHAF1B and PCNT have been studied in other cancers." (PMID 37894336, 2023).
tumor (16 papers, 2012 to 2025). "Lnc-CHAF1B-2 is a recently discovered lncRNA, and its presence and variation have been associated with the development and prognosis of various types of tumours." (PMID 39747989, 2025). "CHAF1B expression also correlates with Ki-67 percentage and is associated with increased tumour size, poor histological grade, and high mitotic index." (PMID 34073937, 2021). "To confirm whether CHAF1B has a tumor-promoting function in HCC, we performed gain- and loss-of-function studies in Huh7 and HepG2 cell lines." (PMID 41049428, 2025). "CHAF1B protein expression is also a proliferation and prognostic marker for renal cell carcinoma, exhibiting a strong correlation with Ki-67 levels and significant associations with poor differentiation of tumour cells, age, advanced stage, and lower OS." (PMID 34073937, 2021). "Similarly, CHAF1B expression in malignant SGT is associated with tumour recurrence and represents the best prognostic factor for distant metastasis." (PMID 34073937, 2021). "Additionally, higher levels of CHAF1B are associated with increased tumour size, advanced stage, and decreased DFS and OS." (PMID 34073937, 2021). "Lnc-CHAF1B-2, a newly discovered long noncoding RNA (lncRNA), plays a significant role in the evolution and prognosis of diverse neoplasms." (PMID 39747989, 2025). "IHC analysis demonstrated significantly higher CHAF1B expression in tumor tissues compared to adjacent non-tumor tissues." (PMID 41049428, 2025). "These core genes—TRAF4, UBE2L3, FBXO45, UBE2L6, FBXL14, SKP2, CHAF1B, and WDR77—have been implicated in tumor progression in previous studies." (PMID 40990020, 2025). "Higher expression levels of CHAF1B protein correlates significantly with male gender, smoking, squamous subtype, and poor differentiation of the tumour." (PMID 34073937, 2021). "WB confirmed that the CHAF1B expression was up-regulated in the tissues of A549/DDP group, and NCOR2 was up-regulated in the tumor tissues in CHAF1B knockdown group." (PMID 32508530, 2020). "By immunohistochemical detection of tumor proliferation-related index Ki-67, the positive rate of Ki67 in the CHAF1B knockdown group was significantly lower than that in the control group, and the apoptosis index was significantly up-regulated." (PMID 32508530, 2020). "Additionally, CHAF1B overexpression resulted in a marked increase in migration and invasion abilities of the tumor cells." (PMID 41049428, 2025). "Moreover, TCGA-LIHC data showed a positive correlation between CHAF1B expression and tumor grade progression." (PMID 41049428, 2025). "Specifically, assessing whether inhibition of ULK1 affects CHAF1B's protumorigenic role in other tumor types may exhibit important clinical significance." (PMID 37377894, 2023). "Importantly, CHAF1B and Ki67 expression can be used as markers of tumour aggressiveness, and CHAF1B expression levels are the best indicator of benign tumours that trans-differentiate to a malignant phenotype." (PMID 34073937, 2021). "Additionally, CHAF1B levels were weakly but significantly associated with MCM (MCM2 and MCM5) expression in the same subset of tumours." (PMID 34073937, 2021). "Recent studies show that CHAF1B acts as a novel marker of tumor proliferation and prognosis." (PMID 32508530, 2020). "Among them, PHF19, AURKA, CHAF1B and AURKB were up-regulated in the tumor group, NAP1L2, TONSL, SATB2 and HDAC9 were down-regulated in the tumor group." (PMID 38212708, 2024). "The analysis of showed that PHF19, AURKA, CHAF1B and AURKB were up-regulated in the tumor group, NAP1L2, TONSL, SATB2 and HDAC9 were down-regulated in the tumor group." (PMID 38212708, 2024). "In contrast with CHAF1B, CHAF1A protein expression inversely correlates with PCNA levels and is downregulated in aggressive tumours." (PMID 34073937, 2021). "The overexpression of CHAF1B in oral SCC is restricted to HPV-negative tumours, whereas HPV-positive tumours display minimal CHAF1B expression." (PMID 34073937, 2021).
tumor (continued). "In conclusion, we obtained several DEGs in CC and found that overexpression of DNMT1, CHAF1B, CHAF1A, MCM2, KNTC1 in tumor tissues predicted poor survival in CC." (PMID 33616161, 2021). "This study supported the inference that the RNA and protein expression levels of autophagy related gene CHAF1B are highly elevated in HCC patients and are also related with poor survival and a more advanced tumor stage in HCC patients." (PMID 33575221, 2020). "In animal experiments, A549/DDP cells transfected with si-con, si-CHAF1B, and si-CHAF1B + si-NCOR2 respectively were transfected into mice for subcutaneous tumor transplantation." (PMID 32508530, 2020). "Future studies are required to investigate whether CHAF1B interacts with ULK1 in these solid tumors and to further elucidate the potential biological role of this complex in various tumor types." (PMID 37377894, 2023). "The CHAF1B and KNTC1 in CC patients were significantly correlated with tumor purity." (PMID 33616161, 2021). "In carcinoma cell lines, the ERK2 signaling reduces the levels of H3.1/H3.2 by suppressing CHAF1B transcription, thus creating the “space” for gap-filling with H3.3, leading to a HIRA-dependent H3.3 enrichment at the promoter of EMT, resulting in tumor progression and metastasis formation." (PMID 35087762, 2021).
infection (1 paper, 2017). The state of being infected such as from the introduction of a foreign agent such as serum, vaccine, antigenic substance or organism. "Interestingly, transcript levels of genes regulating DNA replication and cell cycle progression (Cdc25c, Fosb, Cdkn3, cyclin E2, Chaf1b, Cdt1) were specifically increased in SkMCs and neurons after infection." (PMID 28775382, 2017).
CHAF1B also shares sentences with these, for which no sentence is quoted: lung carcinoma (3 papers); nasopharyngeal carcinoma (3); salivary gland tumors (3); acute myeloid leukaemia (1); bladder cancer (1); cervical squamous cell carcinoma (1); endometrial tumors (1); gallbladder carcinoma (1); head and neck cancer (1); laryngeal carcinoma (1); lymph node metastasis (1); lymphoma (1); oesophageal cancer (1); ovarian carcinoma (1); renal cell carcinoma (1); squamous cell carcinoma (1).